MDM2 (MDM2 proto-oncogene)
Diseases named in the same sentence as MDM2 in open-access papers (continued):
Sharing a sentence is not in itself a finding about the gene and the disease.
cancer (continued). "Since USP7 is a deubiquitinating enzyme that interacts with Mdm2 and prevents its ubiquitination and degradation, targeting USP7 can be an alternative approach for cancer treatment." (PMID 36180910, 2022). "We analyzed MDM2 and RPL11 expression pattern in different cancer cells using the Cancer Dependency Map (DepMap) Portal database." (PMID 36071402, 2022). "Hinokiflavone treatment resulted in the downregulation of MDM2 and MDMX and induction of apoptosis in various cancer cell lines." (PMID 35625571, 2022). "The effect of CDK inhibitorsflavopiridol, THZ1 and YKL-1-116 on Mdm2 transcription and p53induction was studied using an Mdm2:T2A-GFP reporter; its transactivation inbreast cancer cells (MCF-7 cell line) was quantified." (PMID 34707898, 2021). "Another example includes its involvement in the regulatory framework with Mdm2 and NEDD8, inducing growth advantage in HCC cancer cells." (PMID 33513829, 2021). "We use Genoppi to analyze 16 cell-type-specific protein interaction datasets of four proteins (BCL2, TDP-43, MDM2, PTEN) involved in cancer and neurological disease." (PMID 33972534, 2021). "More than 600 E3 ligases have been found in the human genome; however, only a few E3 ligases have been used in PROTAC designs for various cancer targets, including CRBN, VHL, IAP, MDM2, and β-TrCP." (PMID 34943817, 2021).
cancer (continued). "Overexpression of MDM2 and NFAT1 in cancers is correlated with poor prognosis and inhibition of these proteins is a promising targeting strategy for cancer therapy." (PMID 34575883, 2021). "Mdm2/NEDD8/HuR axis plays an important role in liver malignant transformation and tumor progression, potentially amenable for cancer therapy." (PMID 33513829, 2021). "It was suggested that complex events involved with CTs in the formation of derivative chromosomes contributed to the amplification of cancer-related genes, such as CCND1, CDK4, MDM2 and ERBB219." (PMID 33927198, 2021). "Subsequently, after knockdown of hsa_circ_0000073, the marked downregulation in messenger RNA and protein expression of two cancer-related genes, CCNE2 and MDM2, was verified by qRT-PCR and WB." (PMID 34568326, 2021). "Several of these events involve known cancer-related oncogenes, such as YWHAZ (8q22.3), MDM2 (12q15), and CCNE1 (19q12)." (PMID 33397444, 2021). "In contrast to MDM2, MDM4 is expressed at extremely low levels in adult tissues such as the eye, heart, and lung, but at higher levels in various types of cancer cells." (PMID 34144037, 2021). "Therefore, enhanced MDM2 expression could be one signal for cancer malignancy." (PMID 34384473, 2021). "Subsequently, we selected an enriched pathway (hsa05200: pathways in cancer) and intersected with the top 10 hub genes, and we showed that there are 4 overlapping genes (AKT1, MAPK8, AR, and MDM2)." (PMID 33511213, 2021). "Together, these datasets provide insights into the interactome landscape of BCL2, TDP-43, MDM2, and PTEN, and open potential avenues to explore their links to cancers and neurological disorders based on the newly found cell-type-specific interactions." (PMID 33972534, 2021).
cancer (continued). "Altogether, for the first time in a non-cancer context, we report that high glucose downregulates DROSHA in an MDM2-dependent manner." (PMID 33801773, 2021). "To determine if the downregulation of MDM2 is important for the anti-cancer activity of DIM, we created MDM2 overexpression HCT-116 cells to investigate if exogenous expression of MDM2 would attenuate the anti-cancer activity of DIM." (PMID 32629830, 2020). "Both MDM2 and MDMX (MDM2/X) are significantly overexpressed in cancer cells harboring wild type p537,8." (PMID 32651397, 2020). "The most frequent cMDT among the COSMIC cancer genes were observed for the E3 ubiquitin-protein ligases FBXW7 and MDM2, and the Cyclin-Dependent Kinase CDK4." (PMID 32879328, 2020). "USP7 has been proposed as a therapeutic target in several cancers because it has many reported substrates with a role in cancer progression, including FOXO4, MDM2, N-Myc, and PTEN." (PMID 32210275, 2020).
cancer (continued). "Many E3s including MDM2 and BRCA1 participate in regulating the DNA damage response and cell cycle checkpoints to cancer development." (PMID 33643919, 2020). "We show that CDK9 inhibition or knockdown can have a profound effect on the levels of MDM4 oncoprotein in cancer cells overexpressing MDM4 and human pluripotent stem cells, with a minimal impact on MDM2 expression." (PMID 32934219, 2020). "Since both MDM2 and NFAT1 have independent oncogenic roles in cancer progression and development, simultaneously targeting both proteins represents a novel strategy for cancer treatment." (PMID 32397368, 2020). "In this review, we discuss the oncogenic roles of MDM2 and NFAT1 in cancer cells, and how their interaction affects various steps in carcinogenesis." (PMID 32397368, 2020). "MDM2 binds and degrades Rb directly, thereby inhibiting the Rb-E2F1 interaction and promoting transcription of E2F1 to drive cancer cell proliferation." (PMID 32560270, 2020). "As in cancer cells, MDM4 expression was strongly inhibited by dinaciclib, roscovitine, flavopiridol, atuveciclib, and RO3306 in both lines, while MDM2 levels changed only minimally." (PMID 32934219, 2020). "Our findings provide preclinical evidence for targeting MDM2 as a reasonable approach to overcome T-cell-mediated immune resistance or HPD and to design more effective cancer immunotherapy strategies." (PMID 32655895, 2020). "During oxidative stress and hypoxia, increased mitochondrial MDM2 represses NADH-dehydrogenase 6 (MT-ND6) transcription and decreases respiratory complex I activity, resulting in enhanced cancer cell migration and invasion." (PMID 32397368, 2020). "More importantly, the hsa05200 pathway derived from both ME and CNV signatures, which includes EGFR, KRAS, MDM2, STAT1 and other signature genes identified by us, is shown to be closely related to initiation and progression of cancer." (PMID 32030321, 2020).
cancer (continued). "MDM2 and MDM4 are often overexpressed in cancers and therefore serve as promising therapeutic targets." (PMID 30886745, 2019). "RITA displayed efficient induction of apoptosis by inhibiting MDM2 and MDMX in cancer cells as well as in mouse xenografts." (PMID 31310659, 2019). "Surprisingly, only eight identified genes (CCND1, CDK6, CDKN2A, KDM5A, MDM2, MLL3, PPP2R1A, and RB1) are shared by UniCovEx and CovEx, and they are all NCG cancer genes." (PMID 30828525, 2019). "FGF2 and CHEK4 are up-regulated while the expression of CHEK1, WT1, MDM2, BARD1, BMP2, BAMBI, and SOD2, have been reported to be down-regulated in several cancer subtypes, including CRC." (PMID 31623294, 2019). "MDM2 is a transcriptional target of MYC, which is frequently overexpressed in human cancers and as a central oncogene/driver in many cancers." (PMID 30816344, 2019). "MMP14, MDM2, ERBB2, SKP2 and PTGS2, which were previously identified as OGs in human cancer, also have higher rate of amplification in mutation data." (PMID 31205821, 2019).